PCNA (proliferating cell nuclear antigen)
Diseases named in the same sentence as PCNA in open-access papers (continued):
Sharing a sentence is not in itself a finding about the gene and the disease.
colorectal cancer (65 papers, 2004 to 2025). A primary or metastatic malignant neoplasm that affects the colon or rectum. "As PCNA (proliferating cell nuclear antigen) is a proliferation marker, associated with tumor proliferation and invasiveness in colorectal carcinoma, we aimed at detecting changes in protein synthesis." (PMID 36012587, 2022). "MYC is overexpressed and involved in colitis-associated colorectal cancer; PCNA is also upregulated in colorectal cancer." (PMID 34595169, 2021). "Additionally, the expression of an apoptosis-associated protein Bax was enhanced, whereas the expression of a proliferation-associated molecule PCNA was reduced by BTZ in B-Myb–deleted colorectal cancer cells." (PMID 38565963, 2024). "The meta-analysis results showed that quercetin treatment was strongly correlated with a decrease in PCNA levels, suggesting that quercetin has a significant inhibitory effect on cell proliferation during colorectal cancer treatment." (PMID 40978482, 2025). "For example, USP37 facilitates angiogenesis and metastasis in colorectal cancer by stabilizing β-catenin, while its interaction with PCNA drives osteosarcoma pathogenesis by modulating replication fork progression." (PMID 40926837, 2025). "Among the genes examined, Ki-67, MCL-1, and PCNA have rarely been the primary focus in studies investigating the effect of sodium butyrate on colorectal cancer cells." (PMID 39859117, 2025). "Such a finding correlated with the previous one and confirmed that Uro-B restrained the expression of PCNA in a mouse model of colorectal carcinoma." (PMID 40863335, 2025). "PCNA is a crucial protein for the development of colorectal cancer by participating in DNA replication and repair, which are essential for tumor growth and progression." (PMID 39711544, 2024). "This study further revealed that HMGB1-induced activation of ERK1/2 signaling leads to colorectal cancer carcinogenesis and proliferating cell nuclear antigen (PCNA) expression, which is a key proliferation marker indicating the rate at which cells multiply." (PMID 38725632, 2024). "According to the studies on the proliferating cell nuclear antigen index and cell division rates, for solid tumors such as glioblastoma multiforme and colorectal cancers, the iteration interval T is approximately 8~10 days when AR = 0.02." (PMID 35406417, 2022). "Higher levels of Ki67-positive cells and PCNA-positive cells were detected in mice with colorectal cancer induction." (PMID 34684488, 2021). "It is important in the initiation of colorectal cancer and SATB1 expression in colorectal cancer is associated with the expression of S100A4, MMP2, NF-kB, PCNA, cyclin D1 and β-catenin." (PMID 33356851, 2020). "PCNA, involved in replication and DNA damage response showed an increased expression both in resistant colorectal cancer cell lines as well as in ovarian cancer cell lines." (PMID 31344863, 2019). "Treatment of metformin to colorectal cancer cell lines downregulated expression of genes involved in cell cycle regulation and DNA replication including Mcms and PCNA in colorectal cancer cells resistant to 5-fluorouracil (5-FU, explained below)." (PMID 29651420, 2018). "The role of proliferative marker Ki67 in colorectal cancer patients was also confirmed and consistent with PCNA expression in tumor cells studied in vitro as well as a previous study in CRC patients." (PMID 25986235, 2015). "This study showed that the concentrations of HMGB1 in the culture medium of colorectal cancer cells and cleaved caspase-3 in the colorectal cancer cells were increased after radiation, which parallels the increase in PCNA, a well-known proliferative marker." (PMID 25986235, 2015).
colorectal cancer (continued). "Introduction of S. crispus ethanol extracts before AOM seems beneficial in retarding colorectal cancer formation by preventing cell proliferation and inhibiting the activation of PCNA and Bcl2." (PMID 26307342, 2015). "In several studies over-expression (Cyclin D1, NF-κB, PCNA, MMP-2) or loss of expression (Bcl-2, APC) of these molecules have been found to be associated with more aggressive tumor growth in colorectal cancer." (PMID 23326301, 2013). "TMEM97 cytoplasmic expression was shown to be positively correlated to expression of PCNA; this gene is considered a prognostic factor in the metastasis of colorectal cancer." (PMID 20158880, 2010). "PCNA LI was significantly higher in liver tissue of patients with colorectal carcinoma liver metastases than in patients with benign tumor 7 days after partial hepatectomy (PH)." (PMID 14960204, 2004). "Additionally, PCNA serves as an immunohistochemical proliferative marker with prognostic significance in colorectal cancer, providing insight into both overall and disease-free survival rates." (PMID 41170373, 2025). "Colorectal cancer is characterized by a significant increase in key areas, including: (i) cancer growth markers, specifically PCNA; (ii) cancer metastasis biomarkers, such as MMP-9 level; (iii) inflammation markers, like IL-6; and (iv) DNA fragmentation as an apoptotic biomarker." (PMID 41307829, 2025). "In vivo, orientin administration (10 mg/kg) resulted in antiproliferative effects on 1,2-dimethyl hydrazine (DMH)-induced colorectal cancer in rats, and improved tumor marker levels while decreasing proliferative marker levels, such as proliferating cell nuclear antigen (PCNA) and Ki67." (PMID 32708138, 2020). "This glucan also may prevent colorectal cancer (CRC) incidence along with IBD and reduce the expression of the proliferating-associated marker, proliferating cell nuclear antigen (PCNA) in adenocarcinomas." (PMID 28654020, 2017). "In colorectal cancer cells, CYP1B1 modulates the cell cycle by affecting the expression of the PCNA and FEN1 genes, ultimately promoting proliferation." (PMID 40989158, 2025). "BVES-AS1-201-50aa is a peptide encoded from the transcript BVES-AS, which promotes PCNA expression in colorectal cancer cells, while LINC00954-ORF polypeptide, a 49aa peptide identified very recently, suppresses PCNA levels in pulmonary adenocarcinoma cells." (PMID 40361481, 2025). "For instance, in the context of colorectal cancer, SETD8 has been shown to facilitate carcinogenesis by modulating the expression levels of PCNA, thereby disrupting the normal cellular regulatory mechanisms." (PMID 38987564, 2024). "In conclusion, arbutin showed therapeutic effects against colorectal cancer, explained by its ability to significantly decrease ACF, down-regulate PCNA protein, and up-regulate Bax protein." (PMID 38958363, 2024). "Proliferating cell nuclear antigen (PCNA) is a critical DNA repair protein during DNA replication and its overexpression is correlated with colorectal carcinoma progression and metastasis." (PMID 39711544, 2024). "In colorectal cancer, CsA inhibits tumor growth as a result of lower levels of c-Myc, p21(WAF1/CIP1), and proliferating cell nuclear antigen (PCNA)." (PMID 35717152, 2022). "Reportedly, GSDME-mediated pyroptosis supported the development of colorectal cancer (CRC) via the discharge of HMGB1, which promoted proliferating cell nuclear antigen (PCNA) expression and cancer cell proliferation." (PMID 36387211, 2022).
colorectal cancer (continued). "Briefly, one cell proliferation marker, Ki-67 antigen (Ki-67), was upregulated in the cells with overexpressed GAS2, “Correlation between proliferation markers: PCNA, Ki-67, MCM-2 and antiapoptotic protein Bcl-2 in colorectal cancer”." (PMID 27284567, 2016). "There is some debate as to the utility of Ki-67, PCNA, CCND1, and nm23 expressions as prognostic factors in colorectal cancer." (PMID 26689966, 2015). "In this work, we tested whether UNG2 requires interaction with PCNA and RPA to repair DNA damage in a colorectal cancer model during treatment with pemetrexed or FdU." (PMID 41468733, 2025). "In addition, we analyzed the level of PCNA in tumor samples by immunoblot and immunohistochemical staining, which affirmed that ETV4 promoted colorectal cancer proliferation in vivo." (PMID 41281746, 2025). "PCNA reduction with simultaneous upregulation of tumor suppressors such as p21, p27, and others was observed after treatment with natural and synthetic chalcones on human prostate (PC3), bladder (T24), and colorectal cancer (HCT116) tumor cells." (PMID 39062784, 2024). "Our results indicate that FDG uptake associated significantly with hypoxia, reflected by HIF1α expression, but not with proliferative activity, reflected by PCNA expression; these gastric cancer findings correspond to our previous report on colorectal cancer." (PMID 23718763, 2013). "With the ability of cancer cells to evade cell cycle regulation and apoptosis, PCNA overexpression is commonly observed in various malignancies, including breast cancers, duodenal cancers, non-small cell lung cancer (NSCLC), liver cancer, nasal and paranasal sinus cancers, and colorectal cancer." (PMID 41170373, 2025). "Positive expression rate of PCNA mRNA in colorectal cancer with liver metastasis was higher than those without liver metastasis, so it may be useful for evaluating liver metastasis of cancer cells." (PMID 33665162, 2020). "A study showed that the expression of PCNA, Cyclin-D1, MMP-2, and MMP-9 genes can induce the formation of colorectal cancer and promote cancer cell proliferation, migration, and invasion, suggesting that these genes may be closely related to cell proliferation and migration." (PMID 32733959, 2020). "However, in colorectal cancer, the expression of Aurora members does not correlate with the PCNA expression." (PMID 30478982, 2019). "To determine whether the inhibitory effect of YQFS on cancer growth is related to cell proliferation and apoptosis, we examined the YQFS pro-apoptotic and anti-proliferative activities in colorectal cancer mice via immunohistochemical (IHC) staining for TUNEL and PCNA." (PMID 23506655, 2013). "MKI67 and PCNA were used as positive markers, and CDKN1A was used as a negative marker for cell proliferation in colorectal cancer." (PMID 34548081, 2021).
cervical carcinoma (60 papers, 2004 to 2026). A carcinoma arising from either the exocervical squamous epithelium or the endocervical glandular epithelium. "In this study, we show that the human papillomavirus oncogenes that cause most cervical cancers also increase the levels of a cancer-associated isoform of proliferating cell nuclear antigen (PCNA) known as caPCNA." (PMID 42044624, 2026). "Ki67 and PCNA proteins associated with proliferation were highly expressed in cervical cancer tissues and were decreased in cervicitis tissues, and this difference was significant (Ki67: χ2 = 8.464, P < 0.05; PCNA: χ2 = 22.367, P < 0.01)." (PMID 36694148, 2023). "Previous studies have also pinpointed that increased expression of PCNA is associated with poor 5-year survival and advanced pathological stage in cervical cancer." (PMID 31956363, 2020). "We showed that the down regulation of KAT2B and PCNA expression was associated with a higher risk of cervical cancer." (PMID 30020984, 2018). "Withaferin-A-mediated G2/M phase cell cycle arrest in cervical cancer (Caski) cells was associated with decreased expression of cyclin B1, p34 (Cdc2) and proliferating cell nuclear antigen (PCNA), and diminished phosphorylation of STAT3 at tyrosine 705 and serine 727 residues." (PMID 26959007, 2016). "Further analysis of mRNA expression data retrieved from the DepMap platform confirmed our previous observations and showed a positive correlation between the H2Bub1 score and MKi67 or PCNA in cervical cancer (CC) cell lines." (PMID 40597205, 2025). "Ki67 protein and PCNA protein expression levels were significantly higher in cervical cancer tissues compared with cervicitis tissues." (PMID 36694148, 2023). "Ki67 and PCNA were upregulated in cervical cancer tissues compared with cervicitis tissues and correlated with cancer cell proliferation." (PMID 36694148, 2023). "Proliferating cell nuclear antigen (PCNA) protein was highly expressed in cervical cancer tissues compared with cervicitis tissues [χ2 = 22.367, P < 0.01]." (PMID 36694148, 2023). "Another research found that the target genes CDC45, GINS2, MCM2, and PCNA are important participants of cervical cancer." (PMID 36723760, 2023). "A systematic review showed that the expression of PCNA is closely related to the staging and prognosis of cervical cancer." (PMID 35379200, 2022). "lncRNA CCEPR -The Cervical Carcinoma Expressed PCNA Regulatory LncRNA (CCEPR) is highly expressed in cervical cancer." (PMID 35774512, 2022). "CCHE1 binds to PCNA mRNA and promotes its expression, thereby increasing cervical cancer cell proliferation." (PMID 35262965, 2022). "Univariate Cox regression analysis screened 7 genes (FZR1, IMPDH1, HNRNPCL2, PCNA, GPKOW, XPA, and DDX39A) that were associated with the cervical cancer prognosis." (PMID 35909901, 2022). "We observed that isoflurane promoted the proliferative activity of both cervical cancer cells with increased expression of PCNA and BrdU-positive cells." (PMID 32833118, 2021). "Compared with higher proliferateindex in the control group, the ectopic expression of ZBTB28 inhibited proliferation of cervical cancer xenografts were demonstrated by immunohistochemical staining with a monoclonal antibody against PCNA." (PMID 33931087, 2021). "In this work we show that IGF1R interacts with PCNA after irradiation and HU treatment in HeLa cells (cervical cancer cells) and IGF1R positive fibroblasts." (PMID 32701997, 2020). "Metformin inhibited cervical cancer cell proliferation, cervical cancer xenograft growth, expression of PCNA, p-PI3K and p-Akt." (PMID 32631421, 2020). "Tan IIA treatment led to a dramatic 66% reduction in tumor volume of cervical cancer xenograft athymic nude mice by lowering the expression of proliferation marker; proliferating cell nuclear antigen (PCNA)." (PMID 36046197, 2020). "For instance, lncRNA CCHE1 was reported to promote cervical cancer cell proliferation via upregulating PCNA." (PMID 32943989, 2020).
cervical carcinoma (continued). "LncRNA CCHE1 (cervical carcinoma expressed PCNA regulatory lncRNA) promoted carcinogenesis and indicated a poor prognosis of hepatocellular carcinoma via activation of ERK/MAPK pathway." (PMID 32509569, 2020). "Consistent with the previous findings, our study demonstrated that overexpression of PRDX1 significantly promotes cervical cancer cell proliferation, and enhanced the expression of Nanog, PCNA and Bcl-2 and decreased the expression of BAX." (PMID 31956363, 2020). "Consistent with it, NCAPH was significantly co-expressed with PCNA (a specific marker for proliferation ability) in 308 cases of cervical cancer patients from the cBioportal database." (PMID 33311486, 2020). "To further clarify the role of SMYD2 in proliferation of cervical cancer cells in vitro, we examined the expression level of Ki67 and PCNA, respectively." (PMID 31548876, 2019). "Collectively, our findings combined with reports from other groups suggest that GADD45α represses the nuclear export of APE1 to the cytoplasm via inhibiting NO production and stimulating APE1’s interaction with PCNA in cervical cancer cells." (PMID 29743554, 2018). "In the current study, we investigated the expression of IFITM1, Ki-67, and PCNA proteins in cervical cancer tissues and chronic cervicitis tissues." (PMID 29051711, 2017). "CCEPR (cervical carcinoma expressed PCNA regulatory lncRNA) is a novel identified lncRNA that acts as a potential biomarker and involves in development and progression of cervical carcinoma." (PMID 28574830, 2017). "CCEPR (cervical carcinoma expressed PCNA regulatory lncRNA, GenBank number AK055418) is a novel identified lncRNA with 2504 nucleotides in length and localized at the chromosome 10." (PMID 28574830, 2017). "CCEPR was previously reported to interact with PCNA and regulate cervical carcinoma occurrence and progression." (PMID 28574830, 2017). "Ki-67 and PCNA protein expression levels were significantly higher in cervical cancer tissues than in their corresponding cervicitis tissues (P < 0.05 and P < 0.001, respectively)." (PMID 29051711, 2017). "It has been described that GHRH antagonists also reduce the expression of PCNA in benign prostatic hyperplasia, breast and cervical cancer and non-small cell lung carcinoma cells." (PMID 27448980, 2016). "The next top high degree protein PCNA (proliferating cell nuclear antigen) increases due to different grade of CIN (Cervical intra-epithelial neoplasia) lesions in cervical carcinoma." (PMID 26308848, 2015). "According to this study, chrysin and phosphorylated chrysin effectively inhibited the growth of cervical cancer cells, HeLa, via apoptosis induction and down-regulated the proliferating cell nuclear antigen (PCNA) in the cells." (PMID 20559509, 2010). "Targeting the KIF23/MYH9/MCM2/PCNA axis sensitises cervical cancer cells to cisplatin." (PMID 41940421, 2026). "Furthermore, it downregulated the expression of CD31 and PCNA, thereby inhibiting angiogenesis in cervical cancer." (PMID 38751791, 2024). "RNA pull-down analysis showed that CCHE1 physiologically binds to PCNA mRNA, and the interaction between the two leads to the upregulation of the expression of proliferating cell nuclear antigen (PCNA), a tumor proliferation marker, thereby promoting the proliferation of cervical cancer cells." (PMID 36890809, 2023). "PCNA protein was also measured in 27 cervicitis tissues and 38 cervical cancer tissues by IHC." (PMID 36694148, 2023). "In addition, the high expression of CCHE1 in cervical cancer can combine with PCNA mRNA to up-regulate the expression of PCNA, thereby promoting the proliferation of cervical cancer cells." (PMID 36890809, 2023). "Cervical cancer with high PCNA expression has a lower survival rate and a worse prognosis." (PMID 35379200, 2022).